PWRN4 (Prader-Willi region non-protein coding RNA 4)
Synonyms: LINC01084
Gene: Long non-coding RNA gene on chromosome 15 (23,912,409 to 24,090,821, forward strand). Ensembl gene ENSG00000260232.
Diseases named in the same sentence as PWRN4 in open-access papers:
PWRN4 is named in the same sentence as 2 diseases in open-access papers, as found by Europe PMC text mining. Sharing a sentence is not in itself a finding about the gene and the disease.
PWRN4 shares sentences with these, for which no sentence is quoted: cancer (1 paper); hepatocellular carcinoma (1).